MIR891B (microRNA 891b)
Synonyms: hsa-mir-891b; MIRN891B
Gene: MicroRNA gene on chromosome X (146,001,053 to 146,001,131, reverse strand). Ensembl gene ENSG00000216064.
Gene Ontology:
Biological process: miRNA-mediated post-transcriptional gene silencing
Homologues: Orthologues: macaque mml-mir-891a (100% identical), chimpanzee ptr-mir-891b (99% identical).